CD68 (CD68 molecule)
Diseases named in the same sentence as CD68 in open-access papers (continued):
Sharing a sentence is not in itself a finding about the gene and the disease.
spindle cell neoplasm (2 papers, 2020 to 2021). A benign or malignant neoplasm characterized by the presence of neoplastic spindle cells. "When the immunoprofile is not consistent with that of common spindle cell tumors, immunostaining for FDC markers such as CD21, CD23, and CD35, as well as further immunohistochemistry for D2-40, CD68, EGFR, EBV, and BRAF can be helpful for the diagnosis and subtyping of FDCS." (PMID 34516525, 2021).
Takotsubo cardiomyopathy (2 papers, 2018 to 2021). "As with our experimental model, there was a greater proportion of M1 macrophages (CD68/HLADR or CD68/SOCS3 positive) in myocardial tissue from takotsubo cardiomyopathy patients when compared with control tissue, again reflecting a potential proinflammatory response." (PMID 30623136, 2018). "Similarly, immunostaining of our patient’s endomyocardial biopsy specimen showed CD68+ M1 macrophages, suggesting a role for inflammation in Takotsubo cardiomyopathy and supporting the hypothesis that proinflammatory CD68+ M1 macrophages are a possible biomarker of disease." (PMID 34396344, 2021).
thrombosis (2 papers, 2014 to 2025). "Patients with higher CD68/CD163 ratios had approximately 68% increased odds of developing thrombosis compared to those with lower ratios." (PMID 41239536, 2025). "Examination of the 120 human carotid plaques showed that the extent of ALOX15B staining correlated with staining for the macrophage marker CD68 (rs = 0.45, P<0.0001), as expected, and was higher in carotid plaques with thrombosis compared with no thrombosis." (PMID 24533104, 2014).
acute monocytic leukemia (1 paper, 2021). Acute monoblastic leukemia (AML-M5), is one of the most common subtypes of acute myeloid leukemia (AML) that is either comprised of more than 80% of monoblasts (AML-M5a) or 30-80% monoblasts with (pro)monocytic differentiation (AML-M5b). "CD68, lysozyme, and myeloperoxidase are the most sensitive immunohistochemical markers for detecting monoblasts (acute monocytic leukemia 5) or myelomonoblasts (acute monocytic leukemia 4), which account for the vast majority of leukemias at this age." (PMID 34449594, 2021).
airway hyperresponsiveness (1 paper, 2014). "Significant correlations were found between CD45+ cells, neutrophils, and CD68+ cells and virus load and between neutrophils and T and B lymphocytes and airway hyperresponsiveness, chest symptoms, and reduced lung function, whereas mast cells were related to better lung function." (PMID 24457412, 2014).
allergic rhinitis (1 paper, 2015). Inflammation of the nasal mucous membranes caused by an IgE-mediated response to external allergens. "Similarly there was an increase in the activated CD68–, CD123+ plasmacytoid dendritic cells (DC) in the nasal sub-epithelium 24 hours after birch or timothy pollen allergen challenge in subjects with allergic rhinitis." (PMID 25969994, 2015).
anal carcinoma (1 paper, 2022). "This work describes the experience of a Chilean cancer center using multiplexed immunofluorescence to study a case series of four penile cancers, two anal cancers and one vulvar cancer and simultaneous detection of CD8, CD68, PD-L1, Cytokeratin and Ki-67 in FFPE samples." (PMID 35681797, 2022).
aneurysmal bone cyst (1 paper, 2023). A locally aggressive and destructive benign cystic lesion of the bone. "Similarly, the GCs of aneurysmal bone cyst are known to express CD68 and therefore present an osteoclastic phenotype." (PMID 37509363, 2023).
angioleiomyoma (1 paper, 2025). A benign, slow-growing neoplasm that arises from the dermis or subcutaneous tissue. "Lack of reactivity to neural and histiocytic markers (e.g., S100, SOX10, CD68) helps distinguish angioleiomyomas from other spindle cell neoplasms." (PMID 40755624, 2025). "Markers for neural and histiocytic origin including S100, SOX10, and CD68 were negative, confirming the diagnosis of angioleiomyoma and ruling out peripheral nerve sheath tumors and fibrohistiocytic lesions." (PMID 40755624, 2025).
anthrax infection (1 paper, 2015). An infection caused by Bacillus anthracis bacteria. "We present the first observation of CD68 participation in anthrax infection." (PMID 26091359, 2015).
apical periodontitis (1 paper, 2019). "Apart from vasculogenesis, it has been speculated that immune cells communicate with each other and with endothelial cells in human apical periodontitis through VEGF since clustered ELA2, CD68, CD3 and CD19 immune cells are VEGFA, VEGFR-2, VEGFR-3 and VEGFD positive." (PMID 31166414, 2019).
apocrine carcinoma (1 paper, 2014). "CD68 and S100 aid in the differentiation between a GCT and apocrine carcinoma." (PMID 25364429, 2014).
Ascites (1 paper, 2023). Accumulation of fluid in the peritoneal cavity (between the layers of the peritoneum that lines the abdomen). "Furthermore, presence of ascites, hepatic encephalopathy, and infectious complications were associated with low numbers of CD68+AXL+ cells." (PMID 37004869, 2023).
atopic asthma (1 paper, 2011). An asthma that is characterized by symptoms that are triggered by an allergic reaction caused by inhaled allergens such as dust mite allergen, pet dander, pollen and mold. "Two separate studies reported marked increase in CD68+ macrophages in nonatopic, compared with atopic asthma as shown by an increase in CD68+ or in GMCSF receptor α subunit+ cells." (PMID 23724224, 2011).
atrial fibrillation (1 paper, 2022). A disorder characterized by an electrocardiographic finding of a supraventricular arrhythmia characterized by the replacement of consistent P waves by rapid oscillations or fibrillatory waves that vary in size, shape and timing and are accompanied by an irregular ventricular response. "Infiltration of CD68-positive macrophages and increased expression of IL-6 and transforming growth factor beta (TGFβ), inflammatory factors mainly derived from epicardial adipose tissue, were seen in atrial tissue from patients with atrial fibrillation (AF)." (PMID 36405582, 2022).
autoimmune myocarditis (1 paper, 2021). Autoimmune myocarditis is an autoimmune disease that affects the heart. "Male EAM rats developed autoimmune myocarditis 21 days after immunization with cardiac myosin and CFA in the paw, accompanied by an increased amount of myocardial immune cell infiltrates and CD68+ immune reactive cells." (PMID 34122450, 2021).
Azoospermia (1 paper, 2014). Absence of any measurable level of sperm,whereby spermatozoa cannot be observed even after centrifugation of the semen pellet. "The current paper deals with macrophages (CD68 positive cells) and Leydig cells in patients with nonobstructive azoospermia (NOA)." (PMID 24895614, 2014).
basal cell carcinoma (1 paper, 2022). A carcinoma involving the basal cells. "Shows the T-cell (CD8) and macrophage (CD68) labeling index (LI) and cell count (positive cells/mm2) in basal cell carcinoma (BCC) and cutaneous squamous cell carcinoma (cSCC) in the epithelium, stroma, and tumor invasion front." (PMID 35463364, 2022).
bellini carcinoma (1 paper, 2020). "For example, positive immunophenotypical features of CD68 have been observed in bellini carcinoma, a rare type of renal malignancy, and testicular myeloid sarcoma." (PMID 33104706, 2020).
benign prostatic hyperplasia (1 paper, 2024). A non-cancerous nodular enlargement of the prostate gland. "In the early stages of benign prostatic hyperplasia, CD68(+)CD163(+) anti-inflammatory macrophages are converted to the myofibroblast phenotype and promote stromal fibrotic tissue remodeling." (PMID 39261656, 2024).
blue nevus (1 paper, 2018). An intradermal nevus characterized by the presence of benign pigmented dendritic spindle-shaped melanocytes. "Blue nevus is the deposition of stromal melanin characterized by spindle cells within the fibromuscular stroma which stains positive for melanin-specific stains Fontana-Masson and S100 and stains negative for CD68, HMB45, and iron stains." (PMID 29682392, 2018).
bone metastasis (1 paper, 2024). Transfer of a neoplasm from its primary site to bones. "However, CD66b+ neutrophil and CD68+ macrophage counts were unchanged between the primary tumor and bone metastasis FOVs." (PMID 38193534, 2024).
bone sarcoma (1 paper, 2016). A sarcoma that arises from the bone. "In all bone sarcomas, CD68+ TAMs comprised the largest sub-population of inflammatory cells in the tumour followed by CD3+ T cells and DCs." (PMID 27482375, 2016). "Where there was a high number of CD68+ TAMs and CD3+ T lymphocytes in bone sarcomas, DC-SIGN-expressing DCs were noted; some of these cells stained for CD11c and S100 but they did not stain for CD1a." (PMID 27482375, 2016).
bone tumor (1 paper, 2024). "CD68+/CD163+ M2-like immunosuppressive macrophages were also not distinguished between primary breast and bone tumor and stromal tissue segments." (PMID 38193534, 2024).
brain glioma (1 paper, 2012). A malignant glioma that involves the brain. "This concept is further supported here by another murine brain glioma, GL261, in which CD68+ TAMs do not have a preference for PIMO+ hypoxic regions." (PMID 22888475, 2012).
brain inflammation (1 paper, 2022). "Compared to controls (0.1% BSA in 0.9% NaCl), a significant increase of genes related with glia activation (Gfap and Cd68 but not Iba1) but not with brain inflammation (Il-6, Il-1β) was observed at 24 h post-injection." (PMID 35203276, 2022).
breast adenocarcinoma (1 paper, 2022). "We also use 88 duplicate images of the 64-channel CODEX Human FFPE breast adenocarcinoma and test Mistic on seven channels: Keratin14, FoxP3, CD34, CD8, CD3e, CD68, and perlecan." (PMID 35845830, 2022).
breast granular cell tumor (1 paper, 2015). A usually benign neoplasm that arises from the breast. "Histopathologic staining best differentiates breast granular cell tumors from other breast masses with their positive staining for S100, CD68, and neurospecific enolase." (PMID 26491597, 2015).
breast lobular carcinoma (1 paper, 2019). An adenocarcinoma of the breast arising from the lobules. "CD68 was inversely correlated with MYB in breast lobular carcinomas (r = −0.282, p < 0.001, n = 83), only marginal associations were found in ductal and other carcinomas." (PMID 31406165, 2019).
bronchiectasis (1 paper, 2024). Segmental, irreversible dilation of the bronchial tree resulting in the accumulation of secretions which leads to obstruction. "The number of CD3+ T cells was lower in NTM-PD than in bronchiectasis, whereas the number of CD68+ macrophages was higher." (PMID 39138424, 2024).
bronchopneumonia (1 paper, 2025). Acute inflammation of the walls of the terminal bronchioles that spreads into the peribronchial alveoli and alveolar ducts. "The lungs exhibited features consistent with pulmonary edema and chronic emphysema, as well as sequelae of bronchopneumonia, with alveoli filled with necrotic material positive for CD68 and endothelium negative for CD31 in the affected areas." (PMID 41515984, 2025).
cardiac arrest (1 paper, 2020). Cessation of breathing and/or cardiac function. "Unlike the findings observed at 48 h after cardiac arrest, there was a significant decrease in the intensity of CD68 staining in the presence of MCC950 treatment after cardiac arrest." (PMID 32703306, 2020). "As expected, extensive Iba-1-positive, GFAP-positive, and CD68-positive cells appeared in the hippocampal CA1 region in the post-cardiac arrest rats treated with vehicle solution compared to the sham controls." (PMID 32703306, 2020). "However, Ac-YVAD-cmk treatment significantly reduced Iba-1-positive, GFAP-positive, and CD68-positive cells in the hippocampal CA1 region of post-cardiac arrest rats." (PMID 32703306, 2020).
cat-scratch disease (1 paper, 2012). Cat scratch disease is an infectious illness caused by the bacteria bartonella (Bartonella henselae). "Furthermore, inflammatory cells such MBLs, CD68+, CD163+, CD204+ macrophages, S-100+, Langerin+, CD83+, CD163+ dendritic cells and T lymphocytes can be regarded as playing an important role for granuloma formation in tularemia, as in cat scratch disease." (PMID 22588497, 2012).
cheilitis (1 paper, 2023). An inflammatory process affecting the lip. "In the subepithelial region of the Aquitic Cheilitis CD3+ and CD8+ cells showed significant direct correlation (p = 0.035, r = 0.547), as well as CD68+ and CD3+ cells (p = 0.008, r = 0.637) and CD8+ cells (p = 0.017, r = 0.625)." (PMID 38219446, 2023). "In Aquitic Cheilitis, we observed not only a relationship between CD68 with CD3 but of the stimulation of CD68 with CD8 and CD8 with CD3." (PMID 38219446, 2023). "In the Aquitic Cheilitis samples, there was an increase in intraepithelial CD8+ and CD68+." (PMID 38219446, 2023). "The Aquitic Cheilitis showed a significant increase of CD8+ (p < 0.001) and CD68+ (p < 0.001) intraepithelial cells, but not CD3+ or CD20+ cells (p > 0.05)." (PMID 38219446, 2023).
cherubism (1 paper, 2018). Cherubism is a rare, self-limiting, fibro-osseous, genetic disease of childhood and adolescence characterized by varying degrees of progressive bilateral enlargement of the mandible and/or maxilla, with clinical repercussions in severe cases. "TRAP activity, NFATc1 staining and the number of nuclei in CD68+ cells, strongly suggesting an osteoclastic phenotype, seem to be associated with the aggressiveness of cherubism." (PMID 30236129, 2018). "Thus, we showed that human cherubism granuloma is composed mainly of osteoclasts or macrophages and relatively few immune cells, mainly CD68-positive cells, within a fibroblastic environment." (PMID 30236129, 2018).
Cholecystitis (1 paper, 2014). The presence of inflammatory changes in the gallbladder. "The mean number of CD3 positive lymphocytes in the cholecystitis group was 18.6 ± 12.2, but mean number of CD68 positive cells was 29.7 ± 13.9." (PMID 24716194, 2014). "The mean number of CD3 positive lymphocytes in the cholecystitis group was 18.6 ± 12.2, but the mean number of CD68 positive cells was 29.7 ± 13.9." (PMID 24716194, 2014).
Cholestatic liver disease (1 paper, 2022). "As interesting, we found colocalization of CD68 positive macrophages with p62 in the periportal region but not in centrilobular macrophages supporting recent single cell RNA sequencing data identifying multiple populations of macrophages in human cholestatic liver disease." (PMID 36378690, 2022).
chondroblastoma (1 paper, 2023). A benign, chondroid-producing, well-circumscribed, lytic neoplasm usually arising from the epiphysis of long bones. "30–70% of the GCs of chondroblastoma stained CD68-positive, while the GCs of all other lesions stained positive above 70%." (PMID 37509363, 2023). "The same is true for GCs of chondroblastoma, that also showed positive immunoreactivity for CD68, both in the literature and in our study." (PMID 37509363, 2023).
chorioamnionitis (1 paper, 2006). A morphologic finding indicating inflammation of the fetal sac membranes. "The fetal skin from pregnancies with histological chorioamnionitis showed greater infiltration of CD15+ and CD68+ cells than those from pregnancies without histological chorioamnionitis." (PMID 17064297, 2006).
choriocarcinoma (1 paper, 2023). An aggressive malignant tumor arising from trophoblastic cells. "The expression densities of CD68 and GAL-9 were significantly higher in choriocarcinoma than that in PSTT and ETT." (PMID 36875956, 2023). "The Kruskal–Wallis test results showed that the expression density of CD68 and GAL-9 in choriocarcinoma TIIs was significantly higher than that in PSTT and ETT." (PMID 36875956, 2023).
chronic hepatitis B (1 paper, 2021). "Hepatic CD68+ Kupffer cell densities were significantly lower in children compared with adults with IA chronic hepatitis B, without significant differences reached for other immune subsets." (PMID 33621209, 2021).
chronic hepatitis C (1 paper, 2013). "We found that while CD68-negative cell populations, including hepatocytes, contained little or no IL-1β, liver macrophages from chronic hepatitis C patients expressed IL-1β, and CD68-positive cells were present at increased frequency compared with healthy controls." (PMID 23633957, 2013).
chronic pancreatitis (1 paper, 2022). A chronic inflammatory process causing damage and fibrosis of the pancreatic parenchyma. "Compared with DMBA-treated WT mice, DMBA-treated TG mice showed lower mRNA levels of CD68, a marker of macrophages; Cxcl9, a four-chemokine signature in primary and metastatic PC; and Ccl3, which plays an important role during chronic pancreatitis." (PMID 35504863, 2022).
clear cell carcinoma (1 paper, 2022). "However, it should be noted that the samples of papillary RCC were characterized by high content of cells of this type compared to other histological types of RCC—in contrast, for example, to CD68+ cells, the largest number of which was noted in samples of clear cell carcinoma." (PMID 35884821, 2022).
conjunctival melanoma (1 paper, 2021). "For this purpose, we analyzed Ki-67 as a proliferation marker, CD68 as an myeloid cell marker, α-SMA as a marker for perivascular cells, myofibroblasts and smooth muscle cells and granzyme B, which is expressed in cytotoxic T cells in the healthy conjunctiva and in conjunctival melanoma." (PMID 34544377, 2021).
corneal ulcer (1 paper, 2011). Area of epithelial tissue loss from corneal surface; associated with inflammatory cells in the cornea and anterior chamber. "Staining for CD68 showed intense expression on mononuclear cells around the margin of the corneal ulcer in the sample from case 1, but scarcely detected in the control samples." (PMID 21386923, 2011).
cutaneous leishmaniasis (1 paper, 2025). Leishmaniasis affecting the skin. "In cutaneous leishmaniasis, CD68+ macrophages correlated positively with inflammasome markers, whereas in mucocutaneous leishmaniasis, CD163+ cells showed strong negative correlations with IL‐1β and caspase‐1." (PMID 40947759, 2025). "CD68+ and CD163+ macrophages were more abundant in cutaneous leishmaniasis (p < 0.0001 and p < 0.05)." (PMID 40947759, 2025).
cystic fibrosis (1 paper, 2018). Autosomal recessive disorder caused by pathogenic variants in the CFTR gene (cystic fibrosis transmembrane conductance regulator), which encodes a chloride and bicarbonate channel expressed in epithelial cells, and follow the diagnosis criteria. "IL-8, CD68+ macrophages and neutrophils were also significantly elevated in CRSwNP and CRS with cystic fibrosis (CRSwCF) subjects compared to CRSsNP subjects (p-values < 0.05)." (PMID 30283438, 2018).
demyelination (1 paper, 2022). "Therefore, we investigated the local immune response including microglia and macrophages using the markers Iba1 and CD68 expression in our demyelination model." (PMID 35681468, 2022).
dermatomyositis (1 paper, 2025). Dermatomyositis (DM) is a type of idiopathic inflammatory myopathy characterized by evocative skin lesions and symmetrical proximal muscle weakness. "It is important to note that these patients may not have the classic histopathologic findings of dermatomyositis, and biopsy may show an interstitial CD68+ histiocytic infiltrate." (PMID 40225087, 2025).
diabetic neuropathy (1 paper, 2024). A chronic, pathological complication associated with diabetes mellitus, where nerve damages are incurred due to diabetic microvascular injury involving small blood vessels that supply these nerves, resulting in peripheral and/or autonomic nerve dysfunction. "Several publications implicate macrophages in the pathogenesis of diabetic neuropathy, with CD68+ macrophages detectable in sensory ganglia of patients with T2DM and DPN and inflammatory pathways upregulated in macrophages in adipose tissue, foot ulcers, and circulating monocytes." (PMID 38502310, 2024).